CST3 (cystatin C)
Diseases named in the same sentence as CST3 in open-access papers (continued):
Sharing a sentence is not in itself a finding about the gene and the disease.
tumor (continued). "Therefore, serum cystatin C may be a novel biomarker that reflects tumor burden in DLBCL but bears no prognostic significance regarding survival." (PMID 28282874, 2017). "Depleting CST3 or SNCG does not attenuate the formation of RTP cells, but can suppress RTP cells budding with impaired tumor repopulation." (PMID 36658726, 2023).
infection (35 papers, 2011 to 2025). The state of being infected such as from the introduction of a foreign agent such as serum, vaccine, antigenic substance or organism. "In multivariable Cox analysis, the lowest creatinine-cystatin C ratio tertile was associated with an increased risk of infection-related death (aHR 3.763, 95% CI 1.481–9.561; P = 0.005) (model 3)." (PMID 38263396, 2024). "Previous studies have shown that cystatin C and cathepsin L are involved in the rapid responses of both aquatic and terrestrial animals to various stimuli, including lipopolysaccharide (LPS), pathogenic bacteria, and virulent infection." (PMID 40282805, 2025). "Taking into account that the lowest tertile group might be associated with low muscle mass, this is consistent with our finding that infection is the most common cause of death in the lowest creatinine-cystatin C ratio group." (PMID 38263396, 2024). "Infection was the most common cause of death in the lowest creatinine-cystatin C ratio group." (PMID 38263396, 2024). "Regulation of cystatin C may provide a potential clinical avenue for treating infections caused by P. aeruginosa." (PMID 33030263, 2020). "In particular, cystatin C, a member of the cystatin superfamily of cysteine protease inhibitors, has been linked to immune responses to exogenous and endogenous antigens since its encoding gene is modulated by various cytokines during infection and inflammation conditions." (PMID 38245742, 2024). "It was inferred that this result was because AKI was diagnosed using creatinine and cystatin C levels which can be affected by factors other than renal filtration, such as systemic inflammation, which is frequently observed in burned patients with a high risk of infection." (PMID 29944687, 2018). "Macrophages were infected at (MOI 1:10) and P. gingivalis was internalized during the first 3 h of infection, then macrophages were exposed to cystatin C. In 88.54% of the cells and survived inside the macrophage during the next 48 h." (PMID 38708345, 2024). "Altogether, these results demonstrate the potential for a chitosan-particle-based solution to modulate cystatin C expression, overcome the Mtb-induced blockade of the proteolytic function of macrophages, and improve the control of the infection." (PMID 37107091, 2023). "In previous studies, low cystatin C has been shown to decrease infection resistance and exacerbate plaque growth by enhancing chronic low-grade inflammatory stimuli." (PMID 35308546, 2022). "Cystatin C inhibits the growth of P. gingivalis and decreases the inflammatory cytokines, ROS, and NO production during infection of HGFs with P. gingivalis." (PMID 36312752, 2022). "In the late stage of infection, the progression of the disease was impaired by effective elimination of bacteria via innate immunity processes, and the transcription of CST3 was decreased at this time point." (PMID 34952961, 2021). "Changes to kidney (NGAL, Cystatin-C) and infection (MPO, PCT) biomarkers was quantified by means of ELISA, Biomerieux mini-vidas and Konelab 20 analysers." (PMID 32795278, 2020). "In the pathological process of infection and inflammation, the crucial functions of cystatin C need to be emphasized." (PMID 33061826, 2020). "Immunodepletion, co‐immunoprecipitation, and ultracentrifugation determined that the cytoprotective factor released during infection of endothelial cells by P. aeruginosa is cystatin C, which appears to be in a complex with Aβ." (PMID 33030263, 2020). "The data support a model in which the complex of cystatin C and Aβ have a direct cytoprotective role and assist cell survival during the infection process by an undefined mechanism." (PMID 33030263, 2020). "Cystatin B and C levels were also significantly (p ≤ 0.05) reduced during ECTV infection, however the reduction of cystatin C was evident at earlier stages of infection." (PMID 31077130, 2019).
infection (continued). "Our results showed that treatment with cystatin C led to a significant (P = 0.01) 5-fold increase of MTB survival after 24 h of infection in M0 macrophages." (PMID 27572605, 2016). "Nonetheless, inhibition with cystatin C resulted in a significant increase of MTB survival after 24 h of infection in M1 macrophages." (PMID 27572605, 2016). "Inhibition of cathepsin B by the cystatin C expression or by the CA-074Me treatment increases the CD4-independent infection by suppressing the viral particle degradation." (PMID 21541353, 2011). "By screening a cDNA expression library in HeLa cells, cystatin C was isolated as an enhancer of the mNDK infection." (PMID 21541353, 2011). "The spectrum of laboratory abnormalities – spanning hematopoietic (reduced NEUT%, WBC, PLT, eosinophils), hepatic (elevated ALT, AST, LDH), and renal (increased BUN, cystatin C) parameters – mirrors acute-phase dysregulation but persists for years post-infection." (PMID 40794812, 2025). "The obtained results showed that cystatin C could contribute to the inflammatory mediator’s reduction such as NO, which can favor the regulation of tissue damage induced during infection with P. gingivalis." (PMID 38708345, 2024). "Moreover, a growing number of studies have shown conclusively that Cystatin C contributes to the pathophysiology of the immunomodulatory responses seen in inflammatory conditions and infections." (PMID 36361485, 2022). "For example, many factors such as age and T2DM may lead to poorer renal function (and higher cystatin C), which in turn may increase the severity of infection." (PMID 34591027, 2021). "These pathways are mainly involved in innate immune responses, indicating that the immune cells such as PBMCs quickly responded in the early stage of infection, resulting in a large transcription of CST3, which is involved in regulating many pathways of innate immunity and infection control." (PMID 34952961, 2021). "Cytoprotective cystatin C may provide a novel therapeutic avenue for protection against the long‐term consequences of infection with P. aeruginosa." (PMID 33030263, 2020). "Finally, to assess formation of the cystatin C/Aβ complex following infection, PMVECS were treated with PA103 strain of P. aeruginosa for either 0, 2, or 4 h, and the individual supernatants were collected." (PMID 33030263, 2020). "Importantly, data are presented identifying cystatin C as a regulator of cytotoxic activity of Aβ during infection by P. aeruginosa." (PMID 33030263, 2020). "Interestingly, we found a down-regulation for cystatin C in M0 and M1 macrophages upon infection with both mycobacteria species." (PMID 27572605, 2016). "In the hospital setting, rises in cystatin C could reflect inflammation secondary to infection, and the severity of infection, hence an increase in cystatin C, may predict a GFR decline which ultimately impacts vancomycin trough levels." (PMID 24887089, 2014). "However, some studies have shown the relationship between cystatin C and infection." (PMID 35962373, 2022). "This could suggest a sequential action of these two immunoglobulin-degrading proteinases; in the early phase of infection, cystatin C-stabilized IdeS may dominate GAS’s protease activity, followed by SpeB expression and cystatin C degradation at a later stage of infection." (PMID 35008838, 2021). "Because cathepsin B protease, a natural ligand of cystatin C, was upregulated in HeLa cells, we speculated that the high levels of cathepsin B activities were inhibitory to the CD4-independent infection and that cystatin C enhanced the infection by impairing the excessive cathepsin B activity." (PMID 21541353, 2011). "The correlation analysis related to infection revealed the relationship between CRP-proteins and a number of other parameters, such as the biomarkers of kidney function cystatin C as well as the total leukocyte particle concentration (LPC)." (PMID 32576278, 2020).
infection (continued). "We found that the levels of cystatin B and cystatin C in the culture fluids were similar in HIV-1 infected and uninfected MDM throughout the infection." (PMID 22693552, 2012). "Cystatin C expression also enhanced the CD4-dependent infection, but the effect on the CD4-dependent infection was less than that on the CD4-independent infection." (PMID 21541353, 2011). "Cystatin C, which inhibits cystein cathepsin proteases, was isolated as an enhancer of the CD4-independent mNDK vector infection in HeLa cells." (PMID 21541353, 2011). "The differences in TBSA, burn index (BI), infection indicators (leukocytes, C-reactive protein [CRP], and procalcitonin [PCT]), and renal function indicators (Scr, blood urea nitrogen [BUN], and cystatin C [CysC]) between the survival group and the death group were significant (p < 0.05)." (PMID 40590000, 2025). "The group with severe infection had greater values for WBC, AMC, PLT, CRP, ALT, GGT, creatinine, uRBCs, 24 h urine protein, cystatin C, LDH, corrected serum calcium, APTT, D-dimer, and IgE, used more types of immunosuppressants, and had a higher incidence of SRNS." (PMID 41291834, 2025). "Unlike the traditional detection indices, Cystatin C is unaffected by age, sex, race, infection, liver illness, or inflammation." (PMID 36361485, 2022). "Furthermore, these correlations found with neopterin, Gal-9, cystatin C, and TNFRI remained statistically significant when adjusting for estimated duration of infection (EDI)." (PMID 32695109, 2020). "Cystatin C neither inhibited cathepsin B activity nor enhanced the CD4-independent vector infection in 293T cells, probably because the cathepsin B activity of 293T cells was originally low." (PMID 21541353, 2011). "Cystatin C expression did not affect the mNDK vector infection in CD4-negative and –positive 293T cells." (PMID 21541353, 2011). "Collectively, these findings indicate that cystatin C enhances the CD4-independent mNDK vector infection in HeLa and TE671 cells, but does not in 293T cells." (PMID 21541353, 2011). "Cystatin C did not affect the cell surface expression of CXCR4 in HeLa cells, indicating that cystatin C does not increase the CD4-independent vector infection by enhancing CXCR4 expression." (PMID 21541353, 2011). "Since cystatin C is not expressed in 293T cells, cystatin C may not be the factor necessary for the CD4-independent infection in 293T cells." (PMID 21541353, 2011). "The behavior of the type III secretion system and exoenzymes may also help to explain why pelleting of cystatin C and Aβ was only detected when supernatant collected following 4 h infection was analyzed, and not when supernatant collected after 2 h of infection was subjected to ultracentrifugation." (PMID 33030263, 2020).
neurodegenerative disease (32 papers, 2012 to 2025). A disorder of the central nervous system characterized by gradual and progressive loss of neural tissue and neurologic function. "Other significantly downregulated genes were Resp18, Rtn1, Psap, Ubb, Aplp1, Cst3 and Itm2b, which are all associated with neurodegenerative diseases." (PMID 38017352, 2024). "CST3 is also known to be expressed in cerebrospinal fluid and has been proposed as a biomarker for neurodegenerative diseases due to its association with neuronal injury and neuroinflammation." (PMID 38892848, 2024). "Several genes involved in amyloid production were also found to be dysregulated by RH, including Aplp, Rtn1 and Itm2b, all of which have been associated with amyloid beta (Aβ) protein formation, and Resp18, Psap, Ubb and Cst3, all of which are associated with neurodegenerative diseases." (PMID 38017352, 2024). "Moreover, the postnatal brains displayed high expression of Sparc and Cst3 encoding cystatin C, which is involved in CNS neurodegenerative diseases." (PMID 34949203, 2021). "Taken together, these papers show that cystatin C has demonstrably a role in AD and potentially in other neurodegenerative diseases such as PD." (PMID 39958955, 2025). "Previous studies have identified Apoe as a key marker for neurodegenerative diseases while Clu, Cst3, and Mt1 were involved in neuroprotection during aging." (PMID 41370198, 2025). "Both neuroprotective and neurodegenerative roles have been suggested for cystatin C in neurodegenerative disease." (PMID 39958955, 2025). "The cysteine protease inhibitor cystatin C has been described previously as increasing with age and being involved in various neurodegenerative diseases, including AD." (PMID 37341993, 2023). "Inhibitors of cysteine proteases including Cst3 have been shown to be neuroprotective in neurodegenerative diseases." (PMID 36457352, 2022). "It is interesting that those ones which appear in amyloid or neurodegenerative diseases (such as Aβ, cystatin C and prion) have a high probability of behaving as TM proteins." (PMID 33642992, 2021). "CST3 has emerged as a potential neuroprotective and angiogenesis function in neurodegenerative disease like AD, PD, and ALS." (PMID 32733872, 2020). "Cystatin C (CYS C, Cst3) is an endogenous cysteine protease inhibitor that plays neuroprotective roles in neurodegenerative diseases." (PMID 28569795, 2017). "These markers represent various physiological processes, such as protein degradation (ubiquitin), protease inhibition (cystatin C and alpha-1-antichymoptrypsin), and inflammation (C3a and C4a) that are known to be represented in neurodegenerative diseases." (PMID 22701795, 2012). "These markers represent various physiological processes such as protein degradation (ubiquitin), protease inhibition (Cystatin C and Alpha-1-antichymotrypsin), and inflammation (C3a and C4a) that are known to be represented in neurodegenerative diseases." (PMID 22701795, 2012). "This proof of concept demonstrates that cystatin C is secreted by various iPD cell models, including MOs, which in turn suggests that cystatin C secretion by MOs might be pertinent in neurodegenerative disease research." (PMID 39958955, 2025). "Hence, the obtained results imply protective mechanisms of ovocystatin in neurodegenerative diseases, which appears to be consistent with earlier findings for cystatin C biological functions." (PMID 35566501, 2022). "Thus, the exosomal release of cystatin C might be an additional mechanism of cystatin C-mediated protection that might be altered in AD and in other neurodegenerative disease." (PMID 29249935, 2017). "This proof of concept demonstrates that cystatin C is secreted by various idiopathic Parkinson's disease cell models, including midbrain organoids, which in turn suggests that cystatin C secretion by midbrain organoids might be pertinent in neurodegenerative disease research." (PMID 39958955, 2025).
neurodegenerative disease (continued). "Worth noting is the significant down-expression of Cst3, Apoe Itm2b, Clu and Atp6v0c, all involved in protecting against neurodegenerative diseases." (PMID 38017352, 2024). "APOE, CST3, and CLU are known to be mainly involved in all three neurodegenerative diseases and, in particular, have a function of binding to amyloid-β or tau protein, indicating an association with features of neurodegenerative diseases due to protein aggregation of misfolded proteins." (PMID 36797805, 2023). "It has been reported that CST3 has protective effects in neurodegenerative diseases, but the role of CST3 on UCB-induced neurotoxicity has not been elaborated." (PMID 37854583, 2023). "Such altered properties of CST3 could be important in the pathophysiology of CAA and neurodegenerative diseases such as ALS." (PMID 34575849, 2021).
kidney (21 papers, 2005 to 2026). "In this study, we evaluated the association between post-transplant creatinine-cystatin C ratio and death with a functioning graft in 1592 kidney transplant recipients." (PMID 38263396, 2024). "This work reports the design of a novel plastic antibody for cystatin C (Cys-C), an acute kidney injury biomarker, and its application in point-of-care (PoC) testing." (PMID 34072661, 2021). "The outcomes of our study aligned with a recent study that suggested that RES could alleviate kidney dysfunction induced by advanced glycation end-products via modulating the levels of inflammatory mediators, including cystatin c." (PMID 38178854, 2024). "The relatively constant amounts of exosomal mRNA for cystatin C may reflect differences in the way constitutively produced ‘housekeeping’ mRNA is packaged into exosomes compared with mRNA for inducible biomarkers of kidney injury." (PMID 24918752, 2014). "Given the cases of elevated serum creatinine, potential acute kidney injury by RBN‐3143 was investigated by exploring any changes in biomarkers of renal function, including creatinine, urea, and cystatin C (where available)." (PMID 40304706, 2025). "Our data suggest retinol-binding protein (RBP4), beta-2-microglobulin (B2M), cystatin-C (CST3), hepcidin (HAMP), and fatty acid-binding protein (L-FABP) hold promise as candidates for kidney damage surveillance in Bothrops envenoming." (PMID 38536893, 2024). "The positive correlation of urinary VDBP with cystatin C and KIM-1 and day 3 of hospitalisation strongly suggest that renal tubular insult accounts for acute kidney function deterioration in patients with ADHF." (PMID 35757319, 2022). "Of the 18 eV proteins increased in both the native kidney CKD and post-kidney transplant CKD groups, β2-microglobulin and cystatin C were found to correlate significantly with uACR." (PMID 33888746, 2021). "Moreover, increases in the levels of early kidney damage markers were observed after subchronic PM2.5 exposure: the most sensitive markers, β-2-microglobulin and cystatin-C, increased during the first, second, sixth and eighth weeks of exposure." (PMID 27955691, 2016).